HPSE (heparanase)
Diseases named in the same sentence as HPSE in open-access papers (continued):
Sharing a sentence is not in itself a finding about the gene and the disease.
atherosclerosis (continued). "Importantly, increasing clinical and experimental evidence highlights a role for HPSE in the development of atherosclerosis." (PMID 36291066, 2022). "In addition to in vivo HPSE overexpression studies, HPSE inhibitors have also been used in animal models of atherosclerosis." (PMID 36291066, 2022). "Increasing evidence implicates the enzyme HPSE in different stages of atherosclerosis." (PMID 36291066, 2022). "Heparanase upregulation has been identified in many inflammatory diseases including atherosclerosis, fibrosis, and cancer, where it has been shown to play multiple roles in processes such as epithelial-mesenchymal transition, angiogenesis, and cancer metastasis." (PMID 34681753, 2021). "Overexpression of the heparanase gene revealed the importance of HSPGs for the uptake of triglyceride rich lipoproteins (TRPs) and their protective effect on fatty streak formation and potentially atherosclerosis initiation." (PMID 29226146, 2017). "For example, heparanase inhibitors that are being developed as anti-cancer drugs such as PI-88 and glycol-split heparins may also be useful in the treatment of atherosclerosis." (PMID 21483695, 2011). "Therefore, HSPG reduction due to LSS-mediated HPSE expression could, therefore, compromise the function of the endothelium, leading to atherosclerosis." (PMID 36291066, 2022). "Despite an increasing trend towards the use of experimental animal models as well as studies involving pharmacological inhibition of HPSE, the importance and precise roles of HPSE in controlling atherosclerosis and the mechanistic insights into how HPSE promotes this disease remain largely unknown." (PMID 36291066, 2022). "In addition to its inhibitory activity toward heparanase, laminarin sulfate also has other activities that potentially could be useful in treating atherosclerosis." (PMID 30417001, 2018). "Our study demonstrated favorable impact of the heparanase inhibitor PG545 on blood pressure, serum glucose levels, and oxidative stress in apolipoprotein E deficient mice, and as a result one can anticipate a favorable effect towards attenuating atherosclerosis progression by the inhibitor." (PMID 29226146, 2017). "Whether inhibition of heparanase causes attenuation of atherosclerosis progression or not has not been studied so far." (PMID 29226146, 2017). "The involvement of HPSE in tumour progression and metastasis has been extensively studied, however the role of HPSE in CVD, particularly atherosclerosis, is only now emerging." (PMID 36291066, 2022). "Genes such as COMP (cartilage oligomeric matrix protein), CHI3L1, PLA2G2A, P2RY12, CR1, HPSE (heparanase), PTX3 and SERPINE1 were related to atherosclerosis." (PMID 34218797, 2021). "In our study we did not evaluate the direct effect of heparanase inhibition on attenuation of atherosclerosis." (PMID 29226146, 2017). "Although an exact mechanism of action for HPSE in atherosclerosis has not been elucidated, preliminary results from mouse models and evidence of HPSE present in human atherosclerotic samples strongly suggest that HPSE contributes to atherosclerotic disease development." (PMID 36291066, 2022). "The extent of heparanase involvement in atherosclerosis progression has not been studied yet, and it is not clear whether inhibiting heparanase activity would result in reduction of oxidative stress and the resulting attenuation of atherosclerosis progression or not." (PMID 29226146, 2017).
viral infection (23 papers, 2017 to 2025). "In these reports, the authors often used gene downregulation approaches to study the impact of heparanase-1 deficiency on virus infection or exogenously overexpressed heparanase-1." (PMID 36680276, 2023). "Given the modulation of expression during infection, targeting heparanase during viral infection poses both diagnostic and therapeutic potential." (PMID 34681753, 2021). "Cathepsin L expression and consequent heparanase activation have been linked to viral infection and pancreatitis." (PMID 34681753, 2021). "More experimental data are needed to show whether heparanase-1 is implicated in other viral infections with a huge health, social and economic burden, such as human immunodeficiency virus type 1 (HIV-1) and hepatitis B virus (HBV)." (PMID 36680276, 2023). "Heparanase is an endo‐β‐glucuronidase that degrades HS in the extracellular matrix and basement membranes and is implicated in numerous pathological processes such as cancer and viral infections, including SARS−CoV‐2." (PMID 34981584, 2022). "Overall, the emerging knowledge on HPSE as an important regulator of viral infections and associated morbidities could one day make a broad-spectrum antiviral drug a real possibility." (PMID 28927006, 2017). "The focus is on key targets in the viral infection process, including the spike protein, as well as Mpro and HPSE enzymes involved in post-infection viral proliferation and further spread." (PMID 41440920, 2025). "While several past studies have focused on HPSE in viral infections, very little knowledge exists on the role of its competitive inhibitor, HPSE-2." (PMID 39772142, 2024). "We demonstrate that the enhanced expression of HPSE 2, either via viral infection or plasmid transfection, reduces HPSE’s ability to cleave HS, thereby hindering viral egress." (PMID 39772142, 2024). "As well, expression of HPSE is induced and up-regulated during viral infections resulting in degradation of HS and release of pro-inflammatory cytokines." (PMID 36705773, 2023). "HPSE has a crucial role in the activation of macrophage and release of pro-inflammatory cytokines during viral infections." (PMID 36705773, 2023). "Calu-3 cells were first treated with StcE, followed by treatment with heparanase or neuraminidase and subsequent viral infection with SARS2-S pseudotyped VSV-Luc." (PMID 37561789, 2023). "If it can be assumed that heparanase-1 is implicated in numerous viral life cycles, its inhibition by specific heparanase-acting compounds should result in a blockage of viral infection." (PMID 36680276, 2023). "The present review provides a summary of the physiopathology of heparanase-1 in cancer and viral infections with a particular focus on heparanase inhibition as a possible target for the development of novel antiviral strategies." (PMID 36680276, 2023). "Subsequent studies have identified a role of heparanase in penetration of the virus into cells, increasing the severity of viral disease and facilitating viral egress from infected host cells." (PMID 34943994, 2021). "In the context of chronic bacterial and viral infections that can contribute to tumorigenesis, heparanase expression during this inflammatory pre-tumorigenic phase is likely a driver of tumorigenesis." (PMID 34681753, 2021). "Heparanase is widely considered a key player in several diseases including cancer, heart disease, and viral infection." (PMID 34681753, 2021). "Muparfostat inhibition of heparanase activity results in reduced viral infection and cell-to-cell transmission." (PMID 34207476, 2021). "For example, enzymatic removal of specific regions in the HS chain in target cells by using heparanase significantly impairs the viral infection." (PMID 30555321, 2018). "Since the area of research that focuses on mammalian HPSE and viral infections is still emerging only a few papers were found." (PMID 28927006, 2017).
viral infection (continued). "This review will, therefore, outline the versatile roles of HPSE in virus-host interactions and comment on the future potential of HPSE in effective control of human viral diseases." (PMID 28927006, 2017). "Heparanase-1 inhibitors may be considered as dual-acting drugs in cancer treatment and in viral infections and could be used, in theory, for cancer patients with acute or chronic viral infections." (PMID 36680276, 2023). "HPSE is up-regulated in a variety of diseases including virus infections." (PMID 37115924, 2023). "Interestingly, heparanase-1 has also been documented to be involved in numerous viral infections, e.g., HSV-1, HPV, DENV." (PMID 36680276, 2023). "We hypothesized that the increased urinary HPSE levels in PUUV–HFRS could be due to a local increase in the enzyme by the direct viral infection of renal cells." (PMID 35336857, 2022). "Moreover, HSPGs and Heparanase are involved in several viral infections, in which they enhance cell entry and release of the viruses." (PMID 34132790, 2021). "An important role for heparanase during viral infection is emerging and has been recently reviewed." (PMID 34681753, 2021). "Similar to HSPG, heparanase is deeply involved in viral infection and release." (PMID 34132790, 2021). "Interestingly, heparanase (HPSE) activity is shown to be upregulated during virus infection and multiple other diseases assisting in virus replication to promote cell and tissue damage." (PMID 30555321, 2018). "Heparanase was already implicated in inflammation, angiogenesis, and cancer progression and over the past few years significant new progress has been made in elucidating some unique functions of HPSE in viral infection and dissemination." (PMID 28927006, 2017). "Therefore, identifying the epigenetic regulation of OST genes, and HPSE resulting in altered yet specific sulfation patterns in HS chain during virus infection, will be a significant a step toward developing potential diagnostic markers and designing novel therapies." (PMID 30555321, 2018). "Regardless of the undeniable role of heparanase-1 in cancer development and progression, many emerging studies emphasize its involvement in viral infection and pathogenesis." (PMID 36680276, 2023). "A small reduction of viral infection was observed when the cells were treated with only heparanase in comparison to the control cells without treatment." (PMID 37561789, 2023). "Although the authors did show an effect of heparanase-1 exogenous overexpression or downregulation on virus infection, they did not use any pharmacological approach to block heparanase-1 activity." (PMID 36680276, 2023). "Additionally, HPSE expression remained unchanged with CREB3 overexpression; however, it significantly increased with viral infection." (PMID 35746643, 2022). "Genes involved in response to viral infection were not the only genes found to be modulated by heparanase in this study." (PMID 34681753, 2021). "Although a role for heparanase in viral infection has been noticed, the impact of HPSE functional SNPs has not been determined." (PMID 34943994, 2021). "Although a role for heparanase in viral infection has been identified, the impact of HPSE gene functional SNPs has not been determined." (PMID 34943994, 2021). "Several HPSE inhibitors have entered clinical trials for various cancers but none yet for viral diseases." (PMID 28927006, 2017).
glioma (18 papers, 2008 to 2025). A benign or malignant brain and spinal cord tumor that arises from glial cells (astrocytes, oligodendrocytes, ependymal cells). "Previously, we have shown that mRNA level of HPSE is significantly decreased in Grade II-IV gliomas and distribution of its substrate HS is associated with low relapse-free survival of the glioma patients." (PMID 32075104, 2020). "Splice variant 36 of heparanase from Spalax has anti-glioma activity that inhibits HS degradation, suppresses glioma tumor growth and decreases experimental B16-BL6 lung colonization in a mouse model." (PMID 32075104, 2020). "A very recent study using glioma revealed that T5, like heparanase, was associated with the upregulation of CD24, a protein that is significantly associated with malignancy and poor outcomes in a number of carcinomas." (PMID 31850210, 2019). "It is known that different cell types contribute to the increased HPSE expression level in gliomas in vivo (endothelial cells, neutrophils and to some extent glioma cells, the expression of heparanase in which is associated with an elevated Ki67 index)." (PMID 29104277, 2017). "For glioma cells, overexpression of heparanase in U87 cells causes increased phosphorylation of FAK and AKT, decreased phosphorylation of ERK and unchanged phosphorylation of p38." (PMID 18647407, 2008). "Their findings highlight targeting heparanase-exosomal circRNA axis as a promising strategy to overcome TMZ resistance in glioma therapy." (PMID 40427578, 2025). "There was also a study demonstrated that novel HPSE inhibitor can affect the survival of glioma cells by inhibiting autophagy and upregulating apoptosis." (PMID 39990231, 2025). "We have previously shown that HPSE is down-regulated in gliomas Grade II–IV at the mRNA level, and there is a significant decrease of HPSE protein in tumor and paratumorous glioblastoma tissues compared with the normal tissue." (PMID 32075104, 2020). "Previously, a significant decrease of mRNA levels of HPSE in Grade II-IV gliomas and heterogeneous distribution of HPSE protein in primary glioblastomas were demonstrated." (PMID 32075104, 2020). "Overexpression of HPSE in U87 glioma cells increases their invasion, and in U251n also increased cell invasion, proliferation and anchorage-independent colony formation." (PMID 32075104, 2020). "In our study, a predominantly extracellular localisation of anti-HPSE staining was observed, although some glioma cells expressed HPSE as well, supporting the data on the high HPSE expression in glioblastoma cell lines U87 and U251 in vitro." (PMID 29104277, 2017). "The activation of heparanase expression in human U251n glioma cell lines in vitro has been shown to significantly increase cell invasion, proliferation, anchorage-independent colony formation and chemotactic migration of these cells." (PMID 29104277, 2017). "Heterogeneous expression of heparanase in GBM tumours suggests additional regulation of HS content in the glioma tissues at the extracellular level." (PMID 29104277, 2017). "who showed that PG545 inhibited heparanase-induced autophagy in heparanase-overexpressing (Hepa) U87 glioma cells, our results clearly identified PG545 as a promoter of autophagy in OvCa cells." (PMID 28169314, 2017). "In another study, overexpression of heparanase in rat C6 glioma cells shows increased phosphorylation of p38, but phosphorylation of ERK remain unchanged." (PMID 18647407, 2008). "In summary, using well described human glioma cell line U251n, we found that heparanase has the potential to regulate tumor cell invasion, chemotactic migration and proliferation." (PMID 18647407, 2008). "In order to distinguish the role of heparanase on cell invasion, MMP-2 and MMP-9, members of the MMP family that is also involved in glioma invasion, was measured using zymography assay and real-time PCR in both heparanase-overexpressing and control cells." (PMID 18647407, 2008).
glioma (continued). "Non enzymatic functions of heparanase include enhanced adhesion of glioma, lymphoma and T cells, mediated by β1-integrin and correlated with Akt, Pyk2 and ERK activation." (PMID 18545691, 2008). "In addition, proteostasis has emerged as a key molecular mechanism in glioma biology, with heparanase (HPSE) shown to promote autophagy and support tumor progression by regulating intracellular stress responses." (PMID 40718795, 2025). "Information about HPSE expression in gliomas is controversial." (PMID 32075104, 2020). "A high level of heparanase expression has also been shown in human gliomas, as compared to normal brain tissue, which correlates with a shorter survival of patients with a high-grade glioma." (PMID 29104277, 2017). "In the present study, we demonstrate that heparanase overexpression in stably transfected human U251n glioma cells results in a marked increase of cell chemotactic migration toward fetal bovine serum (FBS)-supplied medium and stromal cell-derived factor-1 (SDF-1)." (PMID 18647407, 2008). "In the current study, we overexpressed the human heparanase gene in a human U251n glioma cell line." (PMID 18647407, 2008). "GLI1, along with its truncated homolog (TGLI1), which behaves as gain-of-function GLI1, were reportedly shown to mediate angiogenesis in gliomas by targeting the VEGF, MMP2, MMP9, VEGF-C, TEM7, and proangiogenic heparanase (HPSE) genes, respectively." (PMID 35409080, 2022). "It has been shown that exosomal hsa_circ_0042003, mediated by heparanase transfers from temozolomide (TMZ)-resistant glioma cells to drug-sensitive cells, which contributes to TMZ resistance in glioma." (PMID 35070998, 2021). "Whereas, in glioma, PG545 attenuated heparanase augmented autophagy, and this reduced autophagy was associated with decreased cell growth and decreased tumor load." (PMID 31850210, 2019). "Evidence has been presented to suggest that the COOH-terminal domain (C-domain) mediates some of the non-enzymatic functions of heparanase, including Akt phosphorylation and cell proliferation, and it facilitates tumor progression in a glioma xenograft model." (PMID 31850210, 2019). "Heparanase (HPSE), an enzyme responsible for the cleavage of polysaccharide chains of HS in the extracellular matrix and on the cell surface, affects the HS content in gliomas and tumour microenvironments, as well." (PMID 29104277, 2017). "HPSE expression was detected in U343 and LN71 cell lines only, whereas HS was present in all studied cell lines to various degrees, supporting the contribution of different glioma cell subtypes to intratumoral heterogeneity of HPSE protein and HS content in GBM tumors." (PMID 32075104, 2020). "There is no consensus about HPSE expression in gliomas in the previously published data." (PMID 32075104, 2020). "HPSE transcription is up-regulated in glioma (Grade II-IV) compared with nonmalignant brain tissue." (PMID 32075104, 2020). "Nevertheless, the data on heparanase in gliomas are not very abundant, and are contradictory." (PMID 29104277, 2017). "Remarkably, tumor xenografts produced by C-domain-transfected glioma cells grew faster and appeared indistinguishable from those produced by cells transfected with the full-length heparanase in terms of tumor size and angiogenesis, yielding tumors 6-fold bigger than control." (PMID 23908791, 2011).